SIX1 (SIX homeobox 1)
Diseases named in the same sentence as SIX1 in open-access papers (continued):
Sharing a sentence is not in itself a finding about the gene and the disease.
breast cancer (continued). "In breast cancer cells, the transcription factor SIX1 upregulates aerobic glycolysis and tumor growth by increasing the expression of several glycolytic genes." (PMID 32564010, 2020). "SIX1, which has been reported to be involved in various cancer progressions and correlated with poor prognosis in breast cancer 30, acts as a tumour‐promoting factor by regulating c‐myc, cyclin‐D1 and cyclin‐A1." (PMID 29435409, 2018). "Gene Expression Omnibus database analysis also confirmed that luminal breast cancer patients with SIX1 overexpression had worse overall survival, shorter relapse-free survival, and much worse prognosis." (PMID 30177858, 2018). "The ED mediates the Six1/Eya interaction, which is necessary for Six1 to promote breast cancer metastasis in mouse models." (PMID 29535359, 2018). "Another member of the Six family, SIX1, has been shown to play a role in oncogenic transformation, and recent studies found that the knockdown of SIX1 in breast cancer reduced genomic instability." (PMID 28595628, 2017). "In breast cancer, SIX1 activates extracellular signal-regulated kinase and transforming growth factor-beta signaling pathways, which result in the transformation of mammary epithelial cells and increase the proliferation of cancer stem cells (CSCs)." (PMID 28595628, 2017). "In contrast, EYA1 induces cyclin D1 through its phosphatase activity in breast cancer, and SIX1 directly enhances the transcription of cyclin D1 in rhabdomyosarcoma tumor cells." (PMID 27203207, 2016). "Our analysis indicated that SIX1, SIX2, and SIX4 were associated with clinical prognosis of whole breast cancer population at mRNA level." (PMID 27399099, 2016). "Accumulation of SIX1 reduces paclitaxel sensitivity in patients undergoing breast cancer chemotherapy, and diminishes the therapeutic response to tumor necrosis factor-related apoptosis-inducing ligand (TRAIL) in ovarian carcinoma." (PMID 27203207, 2016). "Overexpression of human Six1 in adult mouse mammary gland epithelium induces aggressive mammary tumor formation and EMT in a dose-dependent manner." (PMID 27916872, 2016). "Increased SIX1–3 expression is linked to high histological grade and ER status, and that SIX2 and SIX3 are upregulated in basal-like breast cancer." (PMID 27399099, 2016). "It actively promotes tumorigenesis of breast cancer by reactivation of Cyclin A1, and c-myc is transcriptionally regulated by Six1 in rhabdomyosarcoma tumor cells." (PMID 23527134, 2013). "Six1 is aberrantly expressed in numerous human tumors such as breast cancer, Wilms’ cancer, and rhabdomyosarcomas." (PMID 23527134, 2013). "This is in line with the previous reports that upregulation of Six1 promotes tumorigenesis in breast cancer, ovarian cancer and hepatocellular carcinoma." (PMID 23527134, 2013). "Recently, some studies have shown that overexpression of Six1 facilitates the metastasis of breast cancer through TGF-β signaling, epithelial-mesenchymal transition, and inducing lymphangiogenesis via upregulation of VEGF-C." (PMID 23527134, 2013). "We demonstrate that Six1 is overexpressed in the CD24low/CD44+ TIC population from human luminal breast cancers, and that it can induce TICs when overexpressed in luminal breast cancer cells via its ability to activate both TGF-β and ERK signaling." (PMID 22765220, 2012). "Together, these data demonstrate that Six1 overexpression in luminal MCF7 breast cancer cells significantly increases the tumor initiating capability of these cells." (PMID 22765220, 2012). "Similar to our observation in human breast cancers xenografted in mice, we detected significantly higher Six1 mRNA in secondary tumorspheres from MCF7 and T47D cells, as compared to their adherent counterparts." (PMID 22765220, 2012). "Taken together, our data present the novel finding that Six1 mediates an increase in the TIC population in luminal breast cancers via activating multiple signaling pathways." (PMID 22765220, 2012).
breast cancer (continued). "Six1 plays an important role in the TIC population in luminal breast cancers and induces a TIC phenotype by enhancing both TGF-β and ERK signaling." (PMID 22765220, 2012). "Mammary-specific overexpression of Six1 in mice induces tumors that resemble human breast cancer, some having undergone epithelial to mesenchymal transition (EMT) and exhibiting stem/progenitor cell features." (PMID 22765220, 2012). "We further demonstrate that the MEK1/2 inhibitor, AZD6244, significantly reduces tumor initiating capability in vivo in breast cancer cells that ectopically and endogenously express high levels of Six1." (PMID 22765220, 2012). "We show for the first time that Six1 expression correlates with poor prognosis in luminal breast cancers and, most significantly, in the aggressive luminal B subtype." (PMID 22765220, 2012). "Nonetheless, taken together, these data suggest that Six1 expression, and the MEK/ERK pathway, activated downstream of Six1, are important for tumor initiation, tumor burden, and subsequent metastasis in an allograft mammary tumor mouse model." (PMID 22765220, 2012). "Nonetheless, taken together these data strongly suggest that Six1 is able to increase the percentage of functional TICs when overexpressed in luminal type mammary carcinoma cells." (PMID 22765220, 2012). "In a parallel study, Micalizzi and colleagues reported that overexpression of SIX1 also facilitated breast cancer metastasis by induction of EMT." (PMID 21952072, 2011). "Six1 is also overexpressed in breast cancers, and it has recently been shown to initiate invasive and aggressive mammary tumorigenesis and metastasis in both transgenic and xenograft mouse models." (PMID 20074369, 2010). "As alluded to above, recent studies describing the role of Six1 in mammary tumor initiation describe a hyperplasia phenotype that arises in aged animals overexpressing Six1." (PMID 20074369, 2010). "We recently demonstrated that Six1 overexpression in the mouse mammary gland is sufficient to induce tumorigenesis, leading to highly aggressive and invasive mammary tumors, many of which undergo an epithelial to mesenchymal transition (EMT)." (PMID 20074369, 2010). "In contrast, Six1 is overexpressed in both primary and metastatic breast tumors, as well as in several human breast cancer cell lines." (PMID 20074369, 2010). "Cyclin A1 is a downstream effector for Six1 in breast cancer where overexpression of Six1 promotes cyclin A1 expression and subsequently increases cell proliferation and progression." (PMID 17008870, 2006). "Overexpression of Six1 occurs in a large percentage of primary breast cancer and strongly correlates with metastatic breast lesions." (PMID 17008870, 2006). "Overexpression of Six1 in breast cancer cells can promote the cancer cells to escape from the G2 cell cycle checkpoint after X-ray irradiation." (PMID 17008870, 2006). "The cell cycle regulatory activity of Six1 in breast cancer is regulated by casein kinase II which inactivates Six1 through phosphorylation." (PMID 17008870, 2006). "Furthermore, overexpression of Six1 has been reported to activate TGF-β signaling in breast cancer, implying a potential profibrotic role of Six1." (PMID 41227354, 2025). "Additionally, we have conducted both in vitro and in vivo experiments to demonstrate the regulatory role of SIX1 in breast cancer stem cells." (PMID 38031089, 2023). "However, the role and mechanism of SIX1 upregulation in breast cancer carcinogenesis remains uncertain." (PMID 38031089, 2023). "Can SIX1 modulate breast cancer progression by regulating stem cells?" (PMID 38031089, 2023). "Furthermore, in breast cancer, SIX1 expression is significantly and positively correlated with Stromal score, indicating an increase in other tumor microenvironment components such as fibroblasts." (PMID 38031089, 2023).
breast cancer (continued). "However, the regulatory role of SIX1 on CSCs in breast cancer primarily pertains to the luminal subtype, while its mechanisms in other subtypes remain largely unexplored." (PMID 38031089, 2023). "Moreover, research has demonstrated that SIX1 plays a unique role in the breast cancer microenvironment." (PMID 38031089, 2023). "In vivo experiments were conducted to investigate the role of Six1 in breast cancer." (PMID 38031089, 2023). "SIX1 is upregulated in different types of tumors, including breast cancer." (PMID 38031089, 2023). "Therefore, we sought to demonstrate the ability of SIX1 to influence breast cancer stem cells by assessing its effect on ALDH activity." (PMID 38031089, 2023). "The interaction between SIX1 and cancer stem cells may play a critical role in regulating breast cancer's initiation and metastasis." (PMID 38031089, 2023). "In this study, we utilized various databases such as UALCAN, TCGA, STRING, and Kaplan–Meier Plotter to investigate the mRNA expression, prognosis, transcriptional profile changes, signal pathway rewiring, and interaction with cancer stem cells of SIX1 in breast cancer." (PMID 38031089, 2023). "Although SIX1 expression was significantly increased in pathological stages 3 and 4 compared to pathological stage 1 in liver and colon cancer samples, a significant increase was detected only in stage 4 compared to stage 1 in breast cancer." (PMID 37427884, 2023). "As recorded in multiple studies, SIX1 can be highly expressed in different tumors, including liver cancer, colorectal cancer, gastric cancer, and breast cancer, thus affecting their clinical prognosis and signal transduction, as well as promoting tumor progression." (PMID 35458126, 2022). "SIX1 could induce vascular endothelial growth factor-C expression, leading to cell migration in breast cancer." (PMID 35287543, 2022). "In recent decades, SIX1 has been reported to be overexpressed in numerous human cancers, such as breast cancer 9, 10, ovarian cancer 11, colorectal cancer 12, thyroid carcinoma 13, and prostate cancer 14, leading to a more aggressive cell phenotype and poorer prognosis." (PMID 35069900, 2022). "SIX1 induced human mammary carcinoma cells to undergo EMT and metastasis through TGF-β signaling." (PMID 35069900, 2022). "In breast cancer cells, Notch signaling was found to be upregulated with Six1 overexpression." (PMID 34490256, 2021). "Besides, decreased DACH1 and increased EYA2 and SIX1 heralded the poor prognosis of breast cancer patients." (PMID 32550045, 2020). "However, we found that when SIX‐1 was overexpressed in breast cancer cells, the multiple of ZEB1 mRNA increase was significantly lower than that of ZEB1 protein increase." (PMID 32227618, 2020). "It was worth mentioning that SIX1 level was positively correlated to DNA repair activity which might contribute to chemotherapy resistance in breast cancer patients with high SIX1 expression." (PMID 32550045, 2020). "Retrieval of the Oncomine database declared that SIX1 was highly expressed in breast cancer." (PMID 33293473, 2020). "Further, mechanistic studies have indicated that SIX1, as an oncogene, is overexpressed in breast cancer, colorectal cancer, esophageal squamous cell carcinoma, and pancreatic cancer, and is associated with the development, progression, and prognosis of multiple tumors." (PMID 30962263, 2019). "Likewise, it has been reported that SIX1 is enriched in cancer stem cells in tumors such as breast carcinoma, glioma and Wilms tumor, and it can promote the acquisition of cancer stem cell features, associated to activation of the TGF-ß or Wnt pathways." (PMID 30723235, 2019).
breast cancer (continued). "EYA2 was required to mediate the pro-metastatic functions of Six1 in breast cancer." (PMID 29340020, 2017). "Six1 also mediates resistance to paclitaxel in breast cancer cells." (PMID 29113360, 2017). "High mRNA level of SIX1 was statistically associated with a poor OS (HR: 1.28, 95% CI: 1.03–1.58; P = 0.963 and I2 = 0.0%) and RFS (HR: 1.28, 95% CI: 1.05–1.56; P = 0.206 and I2 = 26.8%) of whole population of breast cancer." (PMID 27399099, 2016). "For instance, SIX1 was associated with poor OS and RFS of luminal breast cancer patients." (PMID 27399099, 2016). "It has been reported that SIX1 showed great influence on cell proliferation, survival, and motility by transcriptional regulating cyclin D1 and c-myc in rhabdomyosarcoma and cyclin A1 in breast cancer in vitro." (PMID 27821176, 2016). "Moreover, aberrant activation of SIX1 has been reported in tumorigenesis including breast cancer, colorectal cancer and hepatocellular carcinoma, highlighting its oncogenic potential." (PMID 26473286, 2015). "Moreover, SIX genes are deregulated in several types of malignancies, including breast cancer and hepatocellular carcinoma (SIX1), lung cancer (SIX2), chondrosarcoma (SIX3), and acute T-cell leukemia (SIX6)." (PMID 26473286, 2015). "Our laboratory has demonstrated that Six1 mediates tumour initiation, growth and metastasis in mouse models of breast cancer, likely in part through its ability to induce lymphangiogenesis, epithelial-to-mesenchymal transition and tumour initiating cell characteristics." (PMID 26687066, 2015). "Similarly, the high expression rate of Six1 protein was higher in breast cancers with high Clinical stage (75.0 %, 78/104) compared with those with low Clinical stage (0.5 %, 2/40) (P < 0.001)." (PMID 26161040, 2015). "Moreover, patients with high Six1 expression had poorer prognosis than those with low Six1 expression in late stage breast cancer cases." (PMID 26161040, 2015). "Six1 is misexpressed in numerous cancers including breast cancer." (PMID 24891760, 2014). "In addition to the role of Six1 in the early development, it is often misexpressed in various tumors such as breast cancer, Wilms’ tumors, rhabdomyosarcomas, hepatocellular carcinoma, ovarian cancer, and cervical cancer." (PMID 23527134, 2013). "Interestingly, overexpression of Six1, a major activator of TβRI transcription in breast cancer, increased the CSC pool in breast cancer cells by activating the TGFβ pathway." (PMID 23349840, 2013). "MiR-106b could induce epithelial-to-mesenchymal transition (EMT) and a tumor initiating cell phenotype in breast cancer by targeting Smad7 and Six1 and activating TGF-β signaling." (PMID 24040025, 2013). "Because Six1 expression is increased in TICs of both xenografted human luminal breast cancers and cell lines, we directly assessed whether Six1 overexpression could lead to an expansion of TICs in the MCF7 luminal mammary carcinoma cell line." (PMID 22765220, 2012). "Thus, we examined the expression of Six1 in the putative TIC population from primary human luminal type breast cancers that had been xenografted through NOD-scid IL2Rgnull mice." (PMID 22765220, 2012). "Finally, we demonstrate that Six1 significantly correlates with phosphorylated ERK in human breast cancers." (PMID 22765220, 2012). "Six1 mRNA is overexpressed in 50% of primary breast cancers, and in a much larger 90% percent of metastatic lesions, suggesting that it may be involved in more than just tumor initiation." (PMID 22765220, 2012). "While expression of Six1 could be found in all breast cancer subtypes, to our surprise, the highest levels of Six1 mRNA were found in human epidermal growth factor receptor 2 (Her2)-enriched and luminal B breast cancers." (PMID 22765220, 2012). "In addition, we demonstrate that Six1 mRNA correlates with poor prognosis specifically in luminal type breast cancers." (PMID 22765220, 2012).
breast cancer (continued). "However, as Six1 is strongly correlated with prognosis in human breast cancers, and as its overexpression is observed in as many as 50% to 90% of breast cancers, it is likely that the staining is reflective of Six1 expression." (PMID 22765220, 2012). "Six1 overexpression in human breast cancer cells promotes EMT and metastatic dissemination." (PMID 22765220, 2012). "Indeed, our analysis of Six1 expression in several public microarray datasets from human breast cancers demonstrates that inappropriate overexpression of Six1 correlates significantly with worse survival." (PMID 22765220, 2012). "We hypothesized that Six1 plays a role in the tumor initiating cell (TIC) population specifically in certain subtypes of breast cancer, and that by understanding its mechanism of action, we could potentially develop new means to target TICs." (PMID 22765220, 2012). "Taken together, these data suggest that Six1 overexpression in mammary carcinoma cells may increase the cancer stem cell (CSC) or tumor initiating cell (TIC) population." (PMID 22765220, 2012). "We thus performed shRNA-mediated knockdown of Six1 in the highly metastatic 66Cl4 mouse mammary carcinoma cell line, which expresses high levels of endogenous Six1 and metastasizes from the orthotopic site when injected into syngeneic immunocompetent BALB/c mice." (PMID 22765220, 2012). "Since genes that induce EMT have been shown to increase the metastatic capability of cells, we previously investigated and demonstrated that Six1 overexpression in mammary carcinoma cells induces metastasis in both experimental and orthotopic mouse models of metastasis." (PMID 22765220, 2012). "In addition, we have recently shown that Six1 overexpression can induce metastasis in a xenograft model of breast cancer." (PMID 20074369, 2010). "Indeed, recent studies demonstrate that Six1 overexpression in the adult mouse mammary gland is sufficient for initiating invasive carcinomas, and that its overexpression in xenograft models of mammary cancer leads to metastasis." (PMID 20074369, 2010). "Six1 elevated in breast cancer promotes tumour progression through direct activation of Cyclin A1." (PMID 17008870, 2006). "Six1 is overexpressed in 44% of primary tumours and 90% of metastatic tumours in breast cancer." (PMID 17008870, 2006). "Overexpression of Six1 is potentially related to metastatic status of breast cancer and RMS." (PMID 17008870, 2006). "Gene amplification of Six1 is a probable mechanism contributing to tumorigenesis in breast cancer." (PMID 17008870, 2006). "In particular, SIX1 has been shown to induce EMT and metastasis in breast tumors and implicated in TGF-β regulation of collagen deposition leading to hampered immune infiltration and survival in cancer, while PRDM5 has been linked to pro-metastatic production of collagen in breast cancer." (PMID 39939916, 2025). "Furthermore, in breast cancer patients, we explored the correlation between SIX1 and common tumor." (PMID 38031089, 2023). "However, the precise role and mechanism of SIX1 in regulating breast cancer carcinogenesis, as well as its interaction with other genes in promoting tumorigenesis, remain unclear." (PMID 38031089, 2023). "Therefore, we aimed to investigate whether SIX1 can modulate breast cancer stem cells at a phenotypic level." (PMID 38031089, 2023). "Therefore, our preliminary findings suggest that SIX1 may regulate stem cells in breast cancer positively, but further experimental validation is needed." (PMID 38031089, 2023).